PPARG (peroxisome proliferator activated receptor gamma)
Diseases named in the same sentence as PPARG in open-access papers (continued):
Sharing a sentence is not in itself a finding about the gene and the disease.
Obesity (continued). "This review paper, at crossroads of basic sciences, preclinical, and clinical data, intends to analyse the last research concerning PPARG signalling in obesity and cancer." (PMID 27579030, 2016). "Heterozygous PPARγ mice are resistant to high fat diet (HFD) induced obesity and under these conditions, remained more sensitive to insulin than their WT counterparts." (PMID 27483259, 2016). "As a direct consequence, PPARγ knock out mice fail to develop a functional adipose tissue and are protected from obesity-induced insulin resistance." (PMID 27992530, 2016). "Regulation of PPARγ activation is a primary focus in studies of the control of obesity and type 2 diabetes." (PMID 28042289, 2016). "Toll-like receptor 4- (TLR4-) mediated NF-κB activation in obesity severely impairs cold-induced type 2 immune responses, downregulates PPARγ and PPARα expression, and markedly reduces beige fat development." (PMID 28042289, 2016). "Peroxisome proliferator-activated receptor γ (PPARγ), the chief regulator of adipogenesis, has been acutely investigated as a molecular target for natural products in the development of anti-obesity treatments." (PMID 27669202, 2016). "The agonistic effects of flavonoids on PPARγ-mediated obesity, however, vary according to the chemical characteristics of the flavonoids." (PMID 28042289, 2016). "When a “disease threshold” is reached, in either obesity or cancer, PPARG and VDR expression, respectively, diminishes." (PMID 27579030, 2016). "Understanding the role natural products play, as well as the mechanisms behind their inhibition of PPARγ activity is critical for future research into their therapeutic potential for fighting obesity." (PMID 27669202, 2016). "One of the most plausible and reasonable mechanisms for defective BAT activation in obesity involves the inverse regulation of NF-κB and PPARγ transactivation." (PMID 28042289, 2016). "Phosphorylation at this site is believed to be mediated by Cdk5, which has been shown to be blocked by PPARγ agonists, leading to their obesity-related effects." (PMID 27142691, 2016). "Isorhamnetin treatment inhibited the adipocyte differentiation induced by the PPARγ agonist rosiglitazone, reduced obesity development and ameliorated hepatic steatosis induced by both high-fat diet treatment and leptin deficiency." (PMID 26775807, 2016). "Obesity-related changes in PPARα and PPARγ expression were highly tissue specific, with the expressions of both receptors significantly increased in the liver, yet profoundly attenuated in gWAT of obese mice when compared with matched NC-fed controls." (PMID 27439882, 2016). "In this regard, the activation of PPARγ co-operated with C/EBPα in obesity also play an important regulatory role for the upregulation of miR-96 in the liver." (PMID 28036389, 2016). "The downstream target genes of PPARγ and C/EBPα, such as aP2 and adiponectin, are involved in maintaining the adipocyte phenotype, and resistin has been reported as a link between obesity and diabetes." (PMID 27143989, 2016). "In obesity a variety of cytokines such as TNFα secreted by adipose tissue can induce the Cdk5 dependent PPARγ phosphorylation." (PMID 27483259, 2016). "Understanding the role natural products play, as well as the mechanisms behind their regulation of PPARγ activity is critical for future research into their therapeutic potential for fighting obesity." (PMID 27669202, 2016). "Knockout of N-CoR in mice adipose tissue resulted in obesity likely through PPARG post-translational regulation." (PMID 27685785, 2016). "In obesity, PPARG orchestrates adipocyte maturation and differentiation, harmonising the role of many other players in that process." (PMID 27579030, 2016). "Its anti-obesity action involves the inhibition of Egr2, C/EBPs, and PPARγ pathways in adipose tissues." (PMID 27063434, 2016).
Obesity (continued). "The major lipid storage genes are those for the peroxisome proliferator-activated receptor γ (PPARG 3p25) mainly found in adipose tissue, and furthermore the obesity-related FTO (16q12.2)." (PMID 27147943, 2016). "With an increasing understanding of obesity and its key regulator, PPARγ, investigations into the functional mechanism of PPARγ along with the effective regulators of PPARγ have been largely conducted." (PMID 27669202, 2016). "Recent findings have suggested that dietary flavonoids inhibit adipogenesis during differentiation of preadipocytes and prevent obesity by downregulation of PPARγ expression." (PMID 28042289, 2016). "AMPK agonists and PPARγ antagonists appear to be involved in adipocyte differentiation and thus can be potential drugs for the treatment of obesity." (PMID 26846328, 2016). "In the current study, we investigated leptin and IGF1 signaling due to our observation of increased obesity-related factors such as body weight, serum triglyceride and insulin, and peroxisome proliferator-activated receptor γ (PPARγ) after 56Fe radiation." (PMID 27558773, 2016). "Previous studies on PPARG revealed its contribution in numerous diseases, such as: obesity, T2D, and atherosclerosis as well as in celiac disease." (PMID 27483138, 2016). "The peroxisome proliferator-activated receptor γ (PPARγ) ligands are important therapeutic drugs for the treatment of type 2 diabetes, obesity and cardiovascular diseases." (PMID 28025495, 2016). "Functioning as an essential regulator of adipogenesis, PPARγ has been a critical target in the design and development efforts of numerous anti-obesity drugs." (PMID 27669202, 2016). "The promoting role of PPARG agonists in obesity is well established, but on the contrary these hormones have been shown to be clinically active as antidiabetic drugs." (PMID 27562730, 2016). "Some genes are thought to be involved in the development of T2DM and obesity amongst which, the peroxisome proliferator activated receptor gamma (PPAR-γ) gene." (PMID 27239321, 2016). "Plasma FFAs, elevated in obesity, can activate PPARγ through direct interaction with the ligand-binding domain of this receptor." (PMID 28228803, 2016). "As isorhamnetin inhibited PPARγ-dependent adipocyte differentiation, we next investigated the effect of isorhamnetin on obesity and metabolic disorders induced by high-fat diet." (PMID 26775807, 2016). "Mice with diet-induced obesity were treated with the PPARγ or PPARα agonist, pioglitazone or fenofibrate, respectively." (PMID 26770990, 2016). "Much has been already written about PPARG signalling and its role in conditions such as obesity or diabetes." (PMID 27579030, 2016). "On the other hand, some partial PPARγ agonists decrease weight gain in obesity models, raising the possibility that their effect on weight would be associated with increased browning of WAT, and even increased thermogenesis." (PMID 27138164, 2016). "Perilla leaf extract ameliorates high-fat diet-induced obesity and dyslipidemia by downregulating epididymal adipose tissue genes, including CoA carboxylase and PPARγ." (PMID 25673178, 2015). "In the present study, we determined the effect of chronic pioglitazone treatment on hepatic gene expression profile in diet-induced obesity (DIO) C57BL/6J mice in order to understand the mechanisms of NAFLD induced by PPARγ agonists." (PMID 26035752, 2015). "Although substantially weaker, similar observations were made for PPARγ, a key regulator of AT metabolism, suggesting that the metabolic capacity of SAT is linked with obesity-related epigenetic mechanisms." (PMID 26148147, 2015). "Gene and environment interaction studies have shown a nice association between variants in peroxisome proliferator-activated receptor gamma (PPARG), TCF7L2 and fat mass and obesity-associated protein (FTO) genes, a Western dietary pattern and T2DM." (PMID 25421534, 2014).
Obesity (continued). "In total, 50 obese patients undergoing bariatric surgery were included, and paired samples of visceral adipose tissue (VAT) and subcutaneous adipose tissue (SAT) were examined for gene expression of obesity markers leptin, adiponectin and TNFα and PPARγ." (PMID 24427296, 2014). "Therefore, we hypothesized that PPARγ was a key molecule in the process of RA's improvements in dysregulated lipid metabolism and chronic inflammation in adipose tissue associated with high-fat diet-induced obesity." (PMID 24817881, 2014). "In this study, gene expression values of the obesity marker genes leptin, adiponectin, TNFα and PPARγ were measured in paired SAT and VAT samples of 50 obese patients." (PMID 24427296, 2014). "Two PPARG SNPs (rs1801282 and rs3856806) and 3 CTNNBL1 variants (rs6013029, rs16986921 and rs6020712) showed nominal associations with obesity traits." (PMID 24879436, 2014). "The nuclear receptor peroxisome proliferator activated receptor γ (PPARγ) is such a well described obesity marker gene, highly expressed in AT." (PMID 24427296, 2014). "We have previously demonstrated that UA inhibits adipogenesis through the LKB1/AMPK pathway and promotes lipolysis in adipocytes via the PPARγ signaling, and shows an anti-obesity effect in vivo." (PMID 25329874, 2014). "Elevated muscle PPARγ mRNA expression has been measured with obesity and type II diabetes and is thought to negatively affect insulin resistance." (PMID 25289940, 2014). "As the master regulator of adipogenesis, peroxisome proliferator-activated receptor gamma (PPARG) is required for the accumulation of adipose tissue and hence contributes to obesity." (PMID 24466299, 2014). "The aim was to study the effects of pioglitazone mediated sensitization of peroxisome proliferator-activated receptor gamma (PPAR-γ) on the relationship of Cell death-inducing DFFA-like effector C (CIDEC) with obesity related changes in mice." (PMID 25210844, 2014). "Previous studies showed that PPARγ and adiponectin expression was lower in obesity and type II diabetes." (PMID 24533217, 2013). "PPARγ and C/EBPα, the key adipogenic and lipogenic transcriptional regulators, are crucial to the regulation of obesity and adipocyte differentiation." (PMID 23818922, 2013). "According to some evidences, there are possible mechanisms that influencing diseases related to obesity and therapeutic opportunities for them through PPARγ and several adipokines such as vaspin and RBP4." (PMID 24330836, 2013). "PPARγ is a ligand-activated transcription factor that plays an important role in the regulation of obesity." (PMID 23864899, 2013). "In this study, we examined molecular mechanisms that explain differential effects of a PPARα agonist (fenofibrate) and a PPARγ agonist (rosiglitazone) on macrophages during obesity-induced atherogenesis." (PMID 23620818, 2013). "PPARγ agonists have been reported as a new and potentially efficacious treatment of inflammation, diabetes, obesity, cancer, AD, and schizophrenia." (PMID 23431283, 2013). "In rodent models of metabolic syndrome demonstrating diet-induced hepatic steatosis and obesity, hepatic expression of PPARγ is markedly upregulated." (PMID 23935682, 2013). "In conclusion, our results show important associations of PPARδ rs2016520 and PPARγ rs10865170 with BMI, and the observed PPAR interactions have a combined effect on obesity due to gene–gene interaction among rs2016520, rs9794, and rs10865170." (PMID 23545576, 2013). "Further research to track the PPARγ and adiponectin level along with the pathogenesis of obesity would lead to better understanding of the mechanism." (PMID 23342006, 2013). "Increased phosphorylation of PPARγ was observed in obesity and insulin-resistant conditions, and the involvement of increased activation of erk1/2 was proposed." (PMID 23342006, 2013).
Obesity (continued). "PARP-1 is a critical regulator of peroxisome proliferator-activated receptor gamma (PPARγ2)-dependent gene expression with implications in adipocyte function and obesity-related disease models." (PMID 23800102, 2013). "PPARG activation promotes obesity, despite improved insulin sensitivity in liver and adipose tissue and it is generally overexpressed in steatotic liver." (PMID 24324835, 2013). "AMPK and PPARγ appear to be involved in adipocyte differentiation and maturation and thus can be potential drug targets for the treatment of obesity." (PMID 23818922, 2013). "Previous studies have demonstrated local effects of IL-1β on either adipocytes or hepatocytes, both of which can contribute to hepatic lipid accumulation in obesity: In cultured adipocytes IL-1β was shown to induce lipolysis by down-regulating PPARγ." (PMID 23341960, 2013). "Another study showed that long term over-feeding induced obesity and decreased PPARγ expressions in skeletal muscle and VAT." (PMID 23342006, 2013). "In an effort to selectively study the functional role of liver PPARγ in obesity-induced hepatic inflammation, mice deleted of Pparγ in hepatocytes using the cell type-specific gene-knockout technology were recently established." (PMID 23577023, 2013). "In conclusion, this information indicates that regulatory T cells expressing Pparγ are engaged in suppressing adipose tissue inflammation in obesity." (PMID 23577023, 2013). "In metabolic syndrome, it has been shown with macrophage-specific PPAR-γ knockout mice that PPARγ is essential for AAMΦ maturation resulting in the mice developing diet-induced obesity, insulin resistance, and glucose intolerance." (PMID 21772837, 2012). "PPARγ is generally increased in steatotic livers of both animal models of obesity and human obese patients." (PMID 23024649, 2012). "Serum RBP4 levels are elevated in insulin-resistant mice and humans with obesity and type 2 diabetes, and are normalized by rosiglitazone, a PPARγ agonist." (PMID 23145084, 2012). "Ligands for PPARγ are drugs for type 2 diabetes, and ligands for PPARα are also currently in clinical use for obesity." (PMID 22448168, 2012). "In addition, mice with germline heterozygous deletion of the gene encoding PPARγ resulting in reduced PPARγ activity exhibited increased insulin sensitivity as compared to wild-type mice and were also resistant to high-fat diet-induced obesity and insulin resistance." (PMID 22745632, 2012). "Accordingly, knock-out of Nrf2 decreases PPARγ expression, impairs adipogenesis, and protects mice from obesity." (PMID 22991504, 2012). "Emerging evidence indicates that PPARγ plays a role in the pathogenesis of several pathological processes such as diabetes, obesity, atherosclerosis, and cancer." (PMID 22919364, 2012). "Inhibitors of PPARG activity that reduces adipogenesis and thus serve as the basis for the development of effective anti-obesity drugs have already been identified." (PMID 21943323, 2011). "The mRNA expressions of adipocytokines (adiponectin and tumor necrosis factor (TNF)-α), which are produced in white adipose tissue and play important roles in obesity and diabetes, and PPARγ were measured by real-time RT-PCR." (PMID 21799697, 2011). "As in chronological aging and after serial passage in culture (both of which are associated with increased preadipocyte replicative histories), in obesity adipogenesis, C/EBPα, PPARγ, and their downstream targets are decreased in preadipocytes and fat tissue." (PMID 20701600, 2010). "Just like PPARγ, fatty acid synthesis enzymes such as FASN have been implicated in almost all aspects of human metabolic alterations such as obesity, insulin resistance or dyslipemia." (PMID 20148112, 2010). "Enhanced levels of PPARγ have been observed in the fatty liver of several animal models of obesity and diabetes, including ob/ob, db/db, A-Zip, and KKAγ mice." (PMID 20981297, 2010).
Obesity (continued). "Genes previously-reported to be associated with obesity and that reside within marker intervals at our peak LOD scores include GHRL, PPARG, HTR2A and ESR2." (PMID 21062459, 2010). "The aim of this work is to investigate how FASN and PPARγ expression in human adipose tissue is related to carbohydrate metabolism dysfunction and obesity." (PMID 20148112, 2010). "It is possible that elevated PPARγ expression in ob/ob livers appears to be a pathophysiological response to the severity state of obesity and diabetes." (PMID 20981297, 2010). "Mice homozygous for the S112A mutation are indistinguishable from the wild types on a normal diet, but they are significantly more glucose tolerant in the setting of diet-induced obesity, an effect analogous to the outcome of PPARγ activation by TZD treatment." (PMID 20862367, 2010). "Further studies concerning on how C/EBPβ, C/EBPα and PPARγ regulating human adipocyte differentiation could help to elucidate the molecular mechanism of adipocyte differentiation from human stem cells, help to elucidate the mechanisms underlying human obesity and identify therapeutic targets." (PMID 20459638, 2010). "We show that HFD-induced obesity favors activation of PPARγ while suppressing Runx2 and β-catenin in bone and pre-osteoblasts." (PMID 21060836, 2010). "PPARγ is significantly upregulated by the PPARγ activators in the liver or under certain pathophysiological states (e.g., obesity) although its basal expression is rather low." (PMID 20814441, 2010). "Our results support the view that murine TUSC5 is a PPARγ target gene, but a relationship between Tusc5, obesity, and pharmacological actions of PPARγ agonists remains equivocal." (PMID 20204174, 2009). "PPARγ represents important targets for obesity, obesity-induced inflammation, and metabolic syndrome in general." (PMID 20003221, 2009). "We next compared the methylation status of the PPARγ promoters in adipocytes from wild-type (WT) mice with those from two diabetic mouse models: +Leprdb/+Leprdb and diet-induced obesity mice." (PMID 19589179, 2009). "Resistin has been shown to have significantly lower expression in mouse models of obesity, e.g. ob/ob and db/db mice, but is stimulated by PPARγ agonists." (PMID 18348723, 2008). "With this purpose, we have selected highly informative polymorphisms in CAPN5, PPARG and PPARD genes and analysed it in 1953 individuals in relation to the absence or presence of obesity." (PMID 18657264, 2008). "In aggregate, a slew of attempts to generate molecular geneticmodels that will reveal a role for PPARγ in obesity,insulin resistance, and related metabolic disorders have yieldedpartial success and confounding results." (PMID 17389768, 2007). "The link with obesity andinflammation will be discussed separately for the three PPARisoforms: PPARα, PPARβ/δ, and PPARγ." (PMID 17389767, 2007). "Therefore, deciphering crosstalk between USP17 and the adiponectin–PPARγ axis represents a potential therapeutic target for obesity." (PMID 41584855, 2026). "Adiponectin, a major adipokine mediating protection against obesity and cardiovascular disease, exhibits reciprocal regulation with PPARγ: PPARγ up-regulates adiponectin, while adiponectin enhances PPARγ activity through mechanisms including AMPK signaling and anti-inflammatory effects." (PMID 41584855, 2026). "In vivo research suggests that EPA and DHA may reduce obesity and decrease adipogenesis by overexpressing peroxisome proliferator‐activated receptor‐gamma (PPAR‐γ) and downregulating G‐protein‐coupled receptor 120 (GPR‐120)." (PMID 41473401, 2026). "Therefore, the promotion of browning through the consumption of ingredients with PPARγ agonist activity in daily food is an effective way to prevent obesity." (PMID 40529474, 2025). "The possible reasons have been hypothesised that PPARγ protects the dominance of Th2 response, which may be damaged and convert to Th17 response during obesity." (PMID 40329860, 2025).